IL4 (interleukin 4)
Diseases named in the same sentence as IL4 in open-access papers (continued):
Sharing a sentence is not in itself a finding about the gene and the disease.
typhoid fever (3 papers, 2011 to 2025). A bacterial infectious disorder contracted by consumption of food or drink contaminated with Salmonella typhi. "Their findings suggested that individuals carrying the 2R3R heterozygote of the intronic variable number tandem repeat in the IL4 gene may have a genetic predisposition to typhoid fever." (PMID 40875987, 2025). "Indeed, higher levels of IL-10, as well as IL-4, have been detected in PBMC culture of typhoid fever patients when compared to healthy control subjects." (PMID 21829346, 2011).
vasculitis (3 papers, 2015 to 2025). "Serum concentrations of BAFF, APRIL, and other cytokines, including IL-4, IL-6, IL-10, and IL-13, can be implicated in the differentiation of B-cell lineages, while significant increases in BAFF, APRIL, IL-4, and IL-6 were observed in patients with ANCA-vasculitis." (PMID 40430184, 2025).
vulvovaginal candidiasis (3 papers, 2015 to 2022). Infection of the vulva and vagina with a fungus of the genus CANDIDA. "Genetic polymorphism in innate immunity genes such as mannose-binding lectin (MBL), dectin-1 stop-codon, interleukin 4 (IL-4), and NLRP3 was found to be related to vulvovaginal candidiasis among women with no predisposing factors." (PMID 35832797, 2022).
Achalasia (2 papers, 2015 to 2021). A disorder of esophageal motility characterized by the inability of the lower esophageal sphincter to relax during swallowing and by inadequate or lacking peristalsis in the lower half of the body of the esophagus. "Achalasia patients had significantly higher IL-4+ cell percentage when compared with control group." (PMID 26078981, 2015). "However, IL-4+ cell number was higher in type II and type III achalasia versus type I achalasia." (PMID 26078981, 2015).
Achilles tendinitis (2 papers, 2018 to 2020). "The intratendinous injection of DEX/PMSs into Achilles tendinitis rats both decreased the mRNA levels for these cytokines and increased mRNA levels for anti-inflammatory cytokines IL-4 and IL-10 in tendon tissues." (PMID 32090096, 2020). "In order to investigate the in vivo anti-inflammatory effects of SIM/PMSs on collagenase-induced Achilles tendinitis models, we monitored the mRNA levels of both pro-inflammatory cytokines (MMP-3, COX-2, IL-6, TNF-α, and MMP-13) and anti-inflammatory cytokines (IL-4, IL-10, and IL-13)." (PMID 29534523, 2018).
Acidosis (2 papers, 2020 to 2023). Abnormal acid accumulation or depletion of base. "Acidosis decreased the gene expression of the pro-inflammatory markers Nos2, Ccl2, and IL-6 in IFN-γ/lipopolysaccharide-polarized macrophages, and it increased the expression of anti-inflammatory markers CD206 and Arg1 in IL-4-polarized macrophages." (PMID 32823915, 2020). "Acidosis did not significantly alter the frequency of IFN-γ-producing T cells, IL-4-producing T cells or IL-10-producing T cells ex vivo." (PMID 35708739, 2023).
acute monocytic leukemia (2 papers, 2019 to 2023). Acute monoblastic leukemia (AML-M5), is one of the most common subtypes of acute myeloid leukemia (AML) that is either comprised of more than 80% of monoblasts (AML-M5a) or 30-80% monoblasts with (pro)monocytic differentiation (AML-M5b). "D-4F was used for further research, which demonstrated that D-4F inhibited TGF-β1 induced EMTs in alveolar cells and IL-4 induced alternative activation of macrophage in human acute monocytic leukemia cells." (PMID 37576813, 2023). "Context: We reported that D-4F, an apolipoprotein A-I (Apo A-I) mimetic polypeptide with 18 d-amino acids, suppressed IL-4 induced macrophage alternative activation and TGF-β1 expression in phorbol 12-myristate 13-acetate (PMA) treated human acute monocytic leukemia cells (THP-1)." (PMID 31335245, 2019).
adenovirus infection (2 papers, 2019 to 2021). "IL-4 promotes the production of IgG and IgE by B cells, so an abnormally high level of IL-4 may increase the IgE level in children with adenovirus infection, which may lead to inflammatory changes in the respiratory system." (PMID 34712627, 2021). "Interestingly, we observed for the first time that incubation with recombinant IL-4 can increase adenovirus infection through upregulating the expression of SR-A and integrin receptor on CD14+ monocytes." (PMID 30781810, 2019). "To further verify the roles of GM-CSF and IL-4 in promoting adenovirus infection, we detected whether the function blockade of GM-CSF and IL-4 would cripple the adenovirus infection." (PMID 30781810, 2019).
aggressive periodontitis (2 papers, 2015 to 2022). "The gene loci IL-4 −590 and IL-4 −34 are in linkage disequilibrium which has been demonstrated in CP and in aggressive periodontitis (AgP) patients." (PMID 35806269, 2022). "In studies of aggressive periodontitis (PDag) and chronic PD (CPD), 6 proinflammatory mediators (IL-1β, IL-6, IFN-γ, TNF-α, IL-17, and IL-12) and 2 common anti-inflammatory mediators (TGF-β and IL-4) were involved." (PMID 26339136, 2015).
alcohol abuse (2 papers, 2017 to 2023). The use of alcoholic beverages to excess, either on individual occasions ("binge drinking") or as a regular practice. "Alcohol abuse increases IL-4 and IL-10 levels as well as TGF-beta expression in the liver, thus inducing alternatively activated M2 macrophages." (PMID 28566719, 2017).
Alopecia universalis (2 papers, 2010 to 2024). Alopecia universalis is the most severe form of alopecia areata, an inflammatory disease of the hair follicle, which is characterized by a complete loss of hair of the scalp and all the hair-bearing areas of the body. "We found significantly elevated serum IL-4 and total IgE in AA patients (particularly alopecia universalis, AU, and chronic patients) (P < .01)." (PMID 20671941, 2010). "Another case report described a paradoxical increase in cytokines, including IL-4, IL-6, IL-10, IFN-γ, and IL-17, after six months of Tofacitinib treatment in a patient with alopecia universalis." (PMID 39850156, 2024).
anterior uveitis (2 papers, 2022 to 2023). Inflammation of the iris and anterior chamber of the eye. "A slight upregulation of the IL1β and downregulation of IL6, IL4, and CD11b further confirmed a basal complement activation in the blood of patients with anterior uveitis." (PMID 38187376, 2023). "The current study demonstrates that IL-4, IL-6, IL-18, and TNFα have the potential to be relevant in dogs with post-phaco anterior uveitis." (PMID 35998207, 2022). "Also, IL-4, IL-6, IL-18, and TNFα may be important pro-inflammatory cytokines in dogs with anterior uveitis and POH following phacoemulsification (‘POH group’)." (PMID 35998207, 2022). "Dogs with anterior uveitis and POH following phacoemulsification surgery express elevated levels of IL-4, IL-6, IL-18 and TNFα in AH, which is consistent with the human literature." (PMID 35998207, 2022).
anthrax (2 papers, 2011 to 2015). "Interestingly, in the absence of an LT-responsive allele of Nlrp1b, the loss of IL-4 resulted in a slightly higher resistance to anthrax." (PMID 22241984, 2011). "Elevated transcription of TNF-α, IL-1α, IL-1β, IL-4, IL-6, CCL5, CXCL2 and KC have been observed in both murine anthrax challenge models and in vitro macrophages and monocytic cell lines exposed to anthrax antigens." (PMID 26075052, 2015).
anxiety disorder (2 papers, 2024). A category of psychiatric disorders which are characterized by anxious feelings or fear often accompanied by physical symptoms associated with anxiety. "Consistent with this analysis, we found elevated levels of IL-1β, TNF-α, IL-6, and IL-4 expression among children with TD, whereas state anxiety among those children correlated positively with IL-17 levels." (PMID 38956051, 2024). "In individuals with current depressive or anxiety disorders compared to healthy controls, elevated levels were observed in CRP, IL-6, IL-8, IL-18, MCP-1, MIP-1α, MIP-1β, MMP2, and TNF-β, while TNF-α, IL-10, IFN-γ, IL-2, and IL-4 levels either showed no significant elevation or were lower." (PMID 39273641, 2024).
aspergillosis (2 papers, 2023). Aspergillosis is an infection, growth, or allergic response caused by the Aspergillus fungus. "IL-4 is also related to the persistence of Candida albicans in macrophages in vitro and the progression of aspergillosis in mice; therefore, IL-4 may have contributed to the chronicity of CBM in the patients studied here." (PMID 38132773, 2023).
autoimmune hemolytic anemia (2 papers, 2013 to 2017). Autoimmune hemolytic anemia (AIHA) is an autoimmune disorder in which various types of auto-antibodies are directed against red blood cells causing their survival to be shortened and resulting in hemolytic anemia. "The levels of the Th2 type cytokines IL-4, IL-10 and IL-13 are relatively enhanced whereas IFN-γ responses are compromised in thalassemia, sickle cell disease (SCD) and autoimmune hemolytic anemia." (PMID 23358441, 2013).
autoimmune uveitis (2 papers, 2017 to 2021). An autoimmune form of uveitis (disease). "In a recent study in another autoimmune uveitis entity named Vogt-Koyanagi-Harada (VKH) disease, we also found a hypermethylation of the GATA3, IL-4 and TGF-β promoters with a small difference." (PMID 28969068, 2017). "Thus, the role of IL-4 in autoimmune uveitis is still unclear, and no IL-4-related biological agents have been developed, although we often think of IL-4 as an anti-inflammatory cytokine." (PMID 33816637, 2021).
B-cell neoplasm (2 papers, 2013 to 2021). A group of heterogeneous lymphoid tumors generally expressing one or more B-cell antigens or representing malignant transformations of B-lymphocytes. "IL-4 signaling drives proliferation, differentiation, and survival of B lymphocytes from healthy subjects and from diverse B-cell neoplasms such as CLL." (PMID 34449554, 2021). "Second, we set out to investigate whether IL-4 induces DOCK10 in other B-cell neoplasms than CLL, and to analyze the cytoplasmic and nuclear distribution in another CLL patient using appropriate indicators of the purity of the cytosolic and nuclear fractions." (PMID 34449554, 2021).
Babesia infections (2 papers, 2017 to 2023). "Furthermore, IL-6 and IL-4 play a pathogenic role in the persistence of Babesia infections through the inhibition of protective IFN-γ." (PMID 29312230, 2017). "The results indicate that secretion of IL-4 is an antigen-specific reaction induced by the vaccine and it might play a key role in protecting against Babesia infection in the mouse model employed here." (PMID 29312230, 2017). "The data indicate that IL-6 and IL-4 may play a key role in protecting mice from Babesia infection." (PMID 29312230, 2017). "Given that B cells may require assist from T cells to accomplish their differentiation, IL-4 might effect on Babesia infections by inducing antibody generation by B cells when naïve B cells pass through the secondary lymph organs, most notably to the lymphonodus and spleen." (PMID 29312230, 2017). "However, according to the authors’ knowledge, IL-4 levels have not been evaluated in dogs with babesiosis." (PMID 36839438, 2023).
Behçet’s disease (2 papers, 2013 to 2017). "Based on these findings, we decided to investigate the effect of the 70 bp VNTR polymorphism on the third intron of the IL-4 gene in Behçet’s disease." (PMID 23559861, 2013). "The IL-4 gene could be a genetic biomarker in Behçet’s disease in a Turkish study population." (PMID 23559861, 2013).
Bell's palsy (2 papers, 2020 to 2025). Partial or complete paralysis of the facial muscles of one side of a person's face. "Experimentally, increased IL-2 and IL-4 were detected in HSV-1-induced facial nerve palsy as an indication of an immune response." (PMID 41366113, 2025). "Previous studies have revealed that the expression of collagen, IL-1, IL-2, IL-4, TGF-β, and other inflammatory factors is decreased after using high-doses of methylprednisone for femoral head necrosis, shoulder joint injury, spinal cord injury, Bell's palsy, and other diseases." (PMID 32377419, 2020).
bladder tumor (2 papers, 2014 to 2023). "Targeting ILC2s by blocking IL-4/IL-13 signaling pathways, IL-5, or IL-33 receptor, or using IL-33-deficient or ILC2-deficient mice, did not affect mice survival following bladder tumor implantation." (PMID 38283350, 2023). "However, the absence of ILC2s in these mice did not affect the mice survival following bladder tumor challenge, in line with the results obtained when blocking IL-4/IL-13 or IL-5 signaling pathways, or IL-33/ST2 axis." (PMID 38283350, 2023).
blepharitis (2 papers, 2022 to 2024). Inflammation of the eyelids near the eyelashes. "IL-4 and IL-13 are among main cytokines involved in Th2 driven immune response; blocking IL-4 and IL-13 with dupilumab may cause increased risk of eye infections (conjuntivitis, blepharitis, cheratitis) and oral herpes." (PMID 36619513, 2022).
Bovine mastitis (2 papers, 2017 to 2022). INFLAMMATION of the UDDER in cows. "The results of the present study provided the first evidence that the IL-17A promoter polymorphism, whose function is still unclear, is significantly associated with cytokine IL-4 of bovine mastitis." (PMID 28101335, 2017). "Apart from milk somatic cell count (SCC) and somatic cell score (SCS), serum cytokines such as interleukin-17 (IL-17) and interleukin-4 (IL-4) may also be potential indicators for bovine mastitis." (PMID 28101335, 2017). "The serum cytokines, such as interleukin-4 (IL-4), IL-6, IL-17, tumor necrosis factor, and interferon, act as an indirect parameter in inflammatory circumstances, suggesting that serum cytokines, in addition to SCC and SCS, should be included as essential indicators for bovine mastitis." (PMID 36134995, 2022).
Brain atrophy (2 papers, 2012 to 2023). Partial or complete wasting (loss) of brain tissue that was once present. "A relevant study revealed that plasma levels of peripheral inflammatory markers, such as BAFF/TNFSF13B, IL-4, IL-6, IL-17A, and TNF-α, exhibited associations with patterns of brain atrophy, brain hypometabolism, and clinical measures of disease severity and functional status in bvFTD." (PMID 37762113, 2023).
burn (2 papers, 2012 to 2022). A traumatic injury involving interruption of tissue cohesiveness that results from exposure to caustic chemicals, extreme heat, extreme cold or excessive radiation. "Increased levels of IL-1α, IL-2, IL-4, IL-10, IFN-γ and TNFα could be detected in culture media of burn injury skin cultures." (PMID 22359539, 2012).
cardia (2 papers, 2020 to 2022). "In turn, consistently with data regarding interleukin concentration, IL4 expression in gastric tumors tended to increase with the disease advancement." (PMID 32512917, 2020). "Specifically, the elevation of IL-4 in gastric tumors (protein and mRNA) is directly proportional to the disease advancement." (PMID 32512917, 2020).
cervical dysplasia (2 papers, 2014 to 2023). "This study therefore estimated and compared the levels of circulatory IL-4, IL-6, IL-10, TNF-α, and IFN-γ cytokines among adult women identified to have different grades of cervical intraepithelial neoplasia (CIN) and with cervicovaginal infection." (PMID 37635942, 2023). "We have previously shown that the HPV induced cervical dysplasia in patients with decreased serum levels of IFN-γ and IFN-α while increasing the levels of pro-inflammatory cytokines, TNF-α and IL-1β, and cytokine Th-2 type, IL-4." (PMID 24386936, 2014).
chorioamnionitis (2 papers, 2020 to 2025). A morphologic finding indicating inflammation of the fetal sac membranes. "Similarly, six cytokines [e.g., MIP-3α (log2 FC = 5.1), Calgranulin A (log2 FC = 4.5), and IL-4 (log2 FC = 1.8)] showed a significant increase in concentration in preterm labor with intra-amniotic infection compared to preterm labor with sterile intra-amniotic inflammation." (PMID 31945128, 2020).
chronic atrophic gastritis (2 papers, 2009 to 2025). Atrophic gastritis that is persistent and long-standing. "In contrast, the anti-inflammatory Th2 cytokine IL-4 stimulates the secretion of somatostatin, thereby decreasing the development of gastric atrophy." (PMID 19270747, 2009).
colorectal adenoma (2 papers, 2015 to 2019). An adenoma that arises from the colon or rectum. "IL4 and IL4Ra are related to the colorectal adenoma-carcinoma proliferation and the capacity of metastasis." (PMID 31540495, 2019).
coronary atherosclerosis (2 papers, 2019 to 2025). Atherosclerosis of the coronary vasculature. "In this study, we uncover that exosomes produced by human Tohoku Hospital Pediatrics-1 (THP-1) macrophages cultured with the cytokine interleukin-4 (THP1-IL4-exo) reverse cardiac functional decline in mice that developed MI in response to diet-induced occlusive coronary atherosclerosis." (PMID 41047630, 2025).
Cryptococcal meningitis (2 papers, 2019 to 2022). Meningeal inflammation produced by cryptococcus neoformans, an encapsulated yeast that tends to infect individuals with acquired immunodeficiency syndrome and other immunocompromised states. "In fact, IL-4-activated macrophages are associated with uncontrolled cryptococcal meningitis, and the IL-4 level was reported to decrease after effective treatment of oral candidiasis in HIV-infected patients." (PMID 32082071, 2019).
dementia with Lewy bodies (2 papers, 2022 to 2026). "Furthermore, altered levels of interleukin (IL)-10, IL-1β, IL-4, and IL-2 were reported in the MCI stage of dementia with Lewy bodies (DLB) and MCI-AD, thus supporting the role of the peripheral immune system early in the disease process." (PMID 36233411, 2022).
dental pulp inflammation (2 papers, 2021 to 2022). "Pulpitis is characterized by the production of high levels of pro-inflammatory cytokines including TNFα, IL-4, IL-6, IL-8, IL-10 and CXCL8." (PMID 35902880, 2022).
diffuse cutaneous Leishmaniasis (2 papers, 2017 to 2019). A form of LEISHMANIASIS, CUTANEOUS caused by Leishmania aethiopica in Ethiopia and Kenya, L. pifanoi in Venezuela, L. braziliensis in South America, and L. mexicana in Central America. "Patients with localized cutaneous lesion (LCL) exhibit predominant expression of iNOS, IL-1β, IL-6, MCP-1, TNF-α, and IFN-γ, while anergic diffuse cutaneous leishmaniasis (ADCL) lesions are characterized by the presence of IL-4, IL-5, IL-10, and MIP-1α and the low expression of iNOS." (PMID 28959260, 2017).
Down syndrome (2 papers, 2025). "The biomarkers most frequently analyzed in studies of Down syndrome were IL-10, TNF-alpha, IL-1 beta, IL-4, IFN-gamma, and the genes STAT1, STAT3, and SOCS3, all of which are involved in the regulation of the immune response and periodontal inflammation." (PMID 41462866, 2025).
Dry skin (2 papers, 2021 to 2025). Skin characterized by the lack of natural or normal moisture. "In addition, IL-4 reduced the expression of skin barrier proteins, further indicating that the dry skin symptoms were improved through the restoration of the skin barrier protein." (PMID 34579088, 2021).
Duchenne muscular dystrophy (2 papers, 2014 to 2025). Duchenne muscular dystrophy (DMD) is a neuromuscular disease characterized by rapidly progressive muscle weakness and wasting due to degeneration of skeletal, smooth and cardiac muscle. "Contrary to prior data, this study shows that neither eosinophils nor STAT6-mediated IL-4/IL-13 signaling contribute significantly to muscle repair after acute injury or in Duchenne muscular dystrophy (DMD) models." (PMID 39900735, 2025).
eosinophilic pneumonia (2 papers, 2023 to 2025). An inflammatory lung disorder characterized by an increased number of eosinophils in the lungs. "Eosinophilic pneumonia (EP) is a rare but noteworthy adverse effect linked to dupilumab, an interleukin-4 (IL-4) and IL-13 inhibitor used in the managing atopic diseases." (PMID 38259470, 2023).